TRPM8 (transient receptor potential cation channel subfamily M member 8)
Diseases named in the same sentence as TRPM8 in open-access papers (continued):
Sharing a sentence is not in itself a finding about the gene and the disease.
migraine (continued). "TRPA1 and TRPM8 are transient receptor potential channels expressed in trigeminal neurons that are related to pathophysiology in migraine models." (PMID 36272975, 2022). "As commented previously, TRPM8 is expressed in sensory neurons of the peripheral nervous system, including the nerve circuits connected to migraine pathogenesis." (PMID 34445208, 2021). "We further found the pathways “positive regulation of cytosolic calcium ion concentration” and “inositol phosphate-mediated signaling” and hub genes including MEF2D, TSPAN2, PHACTR1, TRPM8 and PRDM16 related to migraine susceptibility." (PMID 32046629, 2020). "TRPM8 is interesting, because genome-wide association studies showed that it may be implicated in migraine, i.e., more specifically, single-nucleotide variants near or within the TRPM8 gene resulting in reduced TRPM8 expression are associated with reduced risk for migraine." (PMID 31948011, 2020). "Within the hub genes detected in our study, TRPM8 gene was found to play an important role in the pathophysiology of migraine." (PMID 32046629, 2020). "Nonetheless, Amgen recently published preclinical pharmacology and human safety data on a novel TRPM8 antagonist proposed to be tested for migraine." (PMID 30970581, 2019). "Reduced TRPM8 expression and function underpins the migraine protection in carriers of rs10166942[C]; thus, the evaluation of TRPM8 antagonists as migraine therapeutics is warranted." (PMID 31873179, 2019). "Ren and colleagues observed that dural application of menthol resulted in inhibition of nocifensive behavior in a mouse migraine model induced by inflammatory mediators, suggesting an anti-nociceptive effect of TRPM8." (PMID 31336748, 2019). "More studies are needed to fully understand the role of TRPM8 in dural afferents and migraine pathophysiology." (PMID 31336748, 2019). "Experimental evidences indicated a role of TRPM8 in cold thermal transduction, different life-threatening tumors, and other pathologies, including migraine, urinary tract dysfunction, dry eye disease, and obesity." (PMID 31141957, 2019). "Since most of the effect on cold pain sensation driven by the homozygotes for the rs10166942[C], we expect a large effect size for migraine protection with full antagonism of TRPM8 supporting an evaluation of TRPM8 antagonists as migraine therapeutics." (PMID 31873179, 2019). "It is worth noting that TRPM8 has been recently proposed as an interesting therapeutic target for migraine due to the analgesic ability of some of its agonists." (PMID 30155469, 2018). "Thus, while the putative influence of rs10166942 in migraine risk is moderate, and additional factors are likely at play, local adaptation in TRPM8 may have contributed to modify, by yet unknown molecular mechanisms, pain-related phenotypes in human populations." (PMID 29723195, 2018). "Perhaps most interesting, however, was that sumatriptan, a drug commonly used to treat migraines, also prevented the migraine-like behaviors, which strongly implicates a role for TRPM8 in migraine generation." (PMID 28358322, 2017). "Development of pharmaceutical antagonists of transient receptor potential melastatin 8 (TRPM8) have been pursued for the treatment of chronic pain and migraine." (PMID 28358322, 2017). "These human studies have naturally sparked interest in exploring the contribution of TRPM8 to migraine through the use of rodent models." (PMID 28358322, 2017). "Again, recent development of TRPA1 and TRPM8 antagonists for pain conditions is likely to promote testing of these drugs in clinical trials for specific migraine and headache conditions." (PMID 27854251, 2016). "This provides a framework to further explore the role of postnatal changes of TRPM8-expressing dural afferents in the pathophysiology of pediatric and adult migraine." (PMID 26111800, 2015).
migraine (continued). "This provides a foundation to further investigate the contribution of postnatal changes of TRPM8-expressing dural afferents to the pathophysiology of pediatric and adult migraine." (PMID 26111800, 2015). "This was surprising, given the implication of TRPM8 in migraine pathophysiology by genetic and functional studies." (PMID 26111800, 2015). "They found a nominal association of four SNPs with migraine with aura: rs2651899 (within the PR domain containing 16 [PRDM16] gene), rs10166942 (near TRPM8), rs12134493 and rs10504861." (PMID 26231841, 2015). "Conversely, topical application of TRPM8 agonist menthol offers pain relief in some migraine patients." (PMID 26111800, 2015). "The TRPM8 single nucleotide polymorphism variant is 950 bp upstream of the transcription start site for TRPM8 mRNA, and has been verified in several migraine cohorts." (PMID 26111800, 2015). "Taken together, this provides a foundation for exploring the contribution of postnatal changes of TRPM8-expressing dural afferents to the pathophysiology of pediatric and adult migraine." (PMID 26111800, 2015). "Since migraine and neuropathic pain share some characteristics, a role for TRPM8 in migraine as well as a link between both pain syndromes is plausible." (PMID 22072275, 2012). "TRPM8 is considered to have a role in animal models of neuropathic pain, a disorder that shares some similarities with migraine." (PMID 22027350, 2011). "In another population-based genome-wide analysis including 5122 migraineurs and 18108 non-migraineurs individuals, rs2651899 (1p36.32, PRDM16) rs10166942 (2q37.1, TRPM8) and rs11172113 (12q13.3, LRP1) were among the top markers associated with migraine." (PMID 22379397, 2011). "Intraperitoneal injections of CGRP, a migraine‐inducing method, do not cause migraine‐like nociceptive behaviors in Trpm8 knockout mice, suggesting that TRPM8 plays an important role in the pathogenesis of migraine." (PMID 41399206, 2025). "Furthermore, the subtype analysis in this meta-analysis concluded that migraine without aura (MO) was significantly associated with seven genetic loci: near TSPAN2, TRPM8, PHACTR1, FHL5, ASTN2, FGF6, and LRP1." (PMID 39850553, 2024). "Although cold temperature and allodynia may suggest a detrimental role for TRPM8, the TRPM8 agonist menthol offers pain relief in some migraine patients." (PMID 37175602, 2023). "However, another study with transgenic mice showed that TRPM8 channels or afferents are both required for the development of acute and chronic migraine-like symptoms." (PMID 37175602, 2023). "Although it is clear that TRPM8 mediates both innocuous and noxious cold sensations, as well as being necessary for cold allodynia and hyperalgesia in various pain models, the role of this channel in migraine-related pain is controversial." (PMID 37175602, 2023). "TRPM8, which functions as a Ca2+-permeable channel, requires the assembly of functional homologous tetramers and plays a vital role in environmental cold sensing, menthol-induced analgesia of acute and inflammatory pain, and migraines." (PMID 35665750, 2022). "TRPM8 antagonists inhibited chronic pain and could be a novel therapeutic target for the treatment of the side effect of chemotherapy in migraine." (PMID 36051440, 2022). "TRPM8 antagonism is deeply related to analgesic in vivo effects and has been proposed as a suitable pharmacological strategy for the treatment of chronic pain, migraine, and painful syndromes." (PMID 35216186, 2022). "These behaviors could be blocked with TRPM8 antagonist and sumatriptan, which further confirms the role of TRPM8 in the development of migraine." (PMID 36614146, 2022). "Furthermore, about 50% of migraine patients have cold allodynia, which further strengthens the role of TRPM8 in the disease." (PMID 36614146, 2022).
migraine (continued). "In this meta-analysis, we investigated the effect of three variants (namely the PRDM16 rs2651899, the rs10166942 near the TRPM8 gene, and the LPR1 rs11172113) on the risk of migraine, as well as on the risk of the main migraine phenotypes, namely the MA and the MO." (PMID 35454329, 2022). "A number of these channels, including transient receptor potential cation channel subfamily A, member 1 (TRPA1); subfamily V, member 1 (TRPV1), subfamily V, member 4 (TRPV4), and subfamily M, member 8 (TRPM8) are highly expressed in primary sensory neurons and play a role in migraine." (PMID 34790097, 2021). "Further investigation regarding the role of TRPM8 in allodynia pathogenesis and migraine chronification may provide a novel treatment strategy." (PMID 31842742, 2019). "However, several genome-wide association studies from different cohorts identified single nucleotide polymorphisms (SNPs) in the gene encoding TRPM8, suggesting an important role for this TRP channel in migraine pathophysiology." (PMID 31336748, 2019). "As such, TRPM8 has begun to gather attention in the migraine field." (PMID 31336748, 2019). "Better understanding of what the SNPs at rs10166942 do to the expression/function of TRPM8 will likely provide much insight into how the channel may be contributing to migraine, whether by greater or lesser activation during attacks." (PMID 30970581, 2019). "In the recent decade, numerous TRPM8 antagonists have been reported by academic groups, as well as pharmaceutical and biotech companies, as potential drugs for neuropathic pain, inflammation, migraine, and cancer." (PMID 31141957, 2019). "Ultimately, TRPM8 activation may act as a migraine initiator in the first instance, but have another role during the neurogenic inflammation phase." (PMID 31336748, 2019). "One of the more intriguing studies related to TRPM8 and migraine in recent years was the finding that the TRPM8 SNP rs10166942 (either C or T at chr2:234835093), which has been identified in GWAS of migraine populations, is differentially expressed across the Earth depending on latitude." (PMID 30970581, 2019). "Together, these new studies support the context-specific role of TRPM8 in migraine." (PMID 30970581, 2019). "Thus, T-allele frequency seems to be predicted by a latitudinal cline, suggesting that human migraine to the colder climates of Northern Europe introduced positive-selection pressure on TRPM8." (PMID 30970581, 2019). "Besides capsaicin, other TRP channel agonists have been described as migraine triggers, thereby placing TRPV1, TRPA1, and TRPM8 in the therapeutic spotlight for the development of migraine treatments." (PMID 30155469, 2018). "Interestingly, migraine leads to increased pain perception of non-noxious cold temperature and ingestion of cold water can in some cases trigger migraine, providing possible links between TRPM8’s mediated cold perception and some aspects of migraine." (PMID 29723195, 2018). "Antagonists of TRPM8 as therapeutics for chronic pain, migraine or inflammation have been pursued over the recent decade by many pharmaceutical companies such as Hydra Biosciences, Glenmark, Janssen, Pfizer, Bayer, Grunenthal, Mitsubishi Tanabe, RaQualia, Dompe/Axxam, BASF, Dendreon and Amgen." (PMID 28358322, 2017). "TRPV1, TRPM8 and TRPA1 have all been linked to migraine pathophysiology." (PMID 27854251, 2016). "Recently, genome-wide studies have provided new insights for genes associated with migraine disease (the ion channel gene, TRPM8, FHL5, ASTN2, and LRP1 but UTS2 gene was not one of them." (PMID 27090416, 2016). "Furthermore, TRPM8 has been shown to form complexes with the 5-HT 1B receptor, a target of the triptan family of anti-migraine drugs, and amplify the analgesic effects of 5-HT 1B agonists." (PMID 26111800, 2015). "We used a behavioral assay to investigate whether and how dural TRPM8 channels regulate the gain of the migraine circuit." (PMID 26111800, 2015).
migraine (continued). "The potential of TRPM8 antagonists as migraine therapeutics is yet to be determined." (PMID 25662185, 2015). "Besides interest in TRPM8 as a temperature sensor and target for migraine, it has also been considered as a potential target for chronic pain based on results in KO mice, receptor expression, and early pharmacology." (PMID 25662185, 2015). "SNP rs7577262 (TRPM8) in particular was highly significant for association with active migraine but not selective for aura or any of the other characteristics." (PMID 24852292, 2014). "In contrast, SNP rs7577262 (TRPM8) was associated with migraine overall and showed little or no selectivity for any of the migraine characteristics." (PMID 24852292, 2014). "SNP rs7577262 (TRPM8) was significantly associated with migraine, correcting for testing across all 10 sub-classifications, but displayed no selectivity for any of the migraine-associated characteristics." (PMID 24852292, 2014). "While the plausible link between PRDM16 and migraine is not obvious, the association of TRPM8 is intriguing." (PMID 22027350, 2011). "Thus, TRPM8 may be considered a potential target for personalized medicine, and the role of menthol may be important in migraine therapy." (PMID 36614146, 2022). "In these neurons, TRPM8 participates in the amplification of pain sensation after injury, suggesting that TRPM8 channel blockers could be effective for the treatment of chronic pain and migraine." (PMID 35216186, 2022). "On the contrary, TRPM8 activation reversed meningeal inflammation-induced lowering of the facial heat pain threshold, and in a trigeminal ganglion cell assay TRPM8 activation inhibited TRPV1 effects, which raised speculations about an antinociceptive activity of TRPM8 in migraine." (PMID 32088764, 2020). "However, the association between the TRPM8 genetic variant and allodynia has never been reported in human studies with migraine." (PMID 31842742, 2019). "It is possible that some migraine triggers may change the composition of phospholipids and/or the level of testosterone in local milieu, thereby altering the activation state of TRPM8 channels in dural afferent fibers as well as the excitability of these neurons." (PMID 26111800, 2015). "It is perhaps relevant that TRPM8, the candidate gene for this SNP, is thought to mediate the sensation of pain rather than specific neurological or vascular functions that might more directly differentiate the pathophysiology of the migraine sub-classes." (PMID 24852292, 2014). "The expression and colocalization of TRPM8 and TRPV1 in TG neurons are increased in a meningeal inflammation‐based migraine model." (PMID 41399206, 2025). "In particular, activated TRPA1, TRPM2, TRPM8, and TRPV1 channels participate in migraine progress through amplifying neuroinflammation." (PMID 41399206, 2025). "The interest in the involvement of TRP channels in migraine pathophysiology is mainly due to their expression on meningeal nociceptors, in particular TRPA1, TRPM8, TRPV1, and TRPV4, and their role in CGRP release from sensory nerve endings upon activation." (PMID 36986537, 2023). "Concerning described TRPM8 antagonists, AMG 333 reached phase 1 clinical trials for the treatment of migraines." (PMID 35269831, 2022). "A recent study points to a functional cross-talk between TRPV1 and TRPM8 in trigeminal ganglion neurons as a possible mechanism for explaining how facial TRPM8 activation can suppress TRPV1 activity, relieving migraine pain." (PMID 34445208, 2021). "Functional TRPM8 alterations have been observed in various inflammatory and neuropathic pain states, including dry eye disease (DED) and migraine, oxaliplatin-based cancer peripheral neuropathy, spinal cord injury, or after sustained morphine administration." (PMID 34445208, 2021).
migraine (continued). "However, transient receptor potential (TRP) channels have been repeatedly linked to the disorder, including TRPV1, TRPV4, TRPM8, and TRPA1, based on their activation by pathological stimuli related to attacks, or their modulation by drugs/natural products known to be efficacious for migraine." (PMID 30970581, 2019). "Therefore, the causal relationship of migraine chronification and TRPM8 variant could not be ascertained." (PMID 31842742, 2019). "Multiple GWAS studies have proposed genes (PRDM16, TRPM8 or LRP1) and locus (Chr8q22.1) to be involved in the migraine." (PMID 24974787, 2015). "Future challenges should be a GWAS in VM patients, since this is a subtype of migraine patients to define endophenotypes and a fine mapping analysis of MTDH, TRPM8 and LRP1 genes in VM." (PMID 22379397, 2011). "TRPM8 has also drawn attention as it is considered as a possible therapeutic target for migraine, neuropathic pain, and non-headache disorders." (PMID 35454329, 2022). "Similarly, the TRPM8 antagonist AMG333, from AMGEN Inc., progressed to a phase one clinical trial (NCT01953341) in healthy subjects and patients with migraine." (PMID 34445208, 2021). "Mechanistically, a functional linkage was observed between TRPM8 and CGRP, that is, CGRP release was deficient in neurons without TRPM8 triggering and the release of CGRP was closely related to neurogenic inflammation and future migraine occurrence." (PMID 32046629, 2020). "The associations of six SNPs identified from our previous study, including TRPM8 rs10166942, LRP1 rs1172113, DLG2 rs655484, GFRA1 rs3781545, UPP2 rs7565931, and GPR39 rs10803531, and migraine endophenotypes, including chronic migraine and allodynia were tested." (PMID 31842742, 2019). "Due to the lack of a mouse model of pediatric migraine, our study did not directly investigate the functional relevance of the reduction of TRPM8-expressing dural afferent fibers before the onset of puberty." (PMID 26111800, 2015). "This prompted us to quantitatively analyze the dural afferent fibers expressing TRPM8 channels to see whether they differ significantly from fibers expressing CGRP, which has a well-established role in migraine pathophysiology." (PMID 26111800, 2015). "In the WGHS, after correcting for multiple testing, fifteen SNPs (including the two TRPM8 SNPs in high LD) were either significant for migraine overall regardless of symptoms or significantly selective for at least aura or one of the diagnostic symptoms for migraine." (PMID 33643179, 2020). "Whereas seven loci (i.e. near TSPAN2, TRPM8, PHACTR1, FHL5, ASTN2, near FGF6, and LRP1) were associated with migraine without aura (in a sample of 8348 cases and 139,622 controls), none were associated with migraine with aura (6332 cases vs. 144,883 controls)." (PMID 32503413, 2020). "An indication for which antagonism of TRPM8 may still hold therapeutic promise is migraine, though the lack of validated preclinical migraine models leaves the promise to be revealed in the clinic." (PMID 25662185, 2015). "Finally, the associations seen for rs2651899 (PRDM16) and rs10166942 (TRPM8), but not rs11172113 (LRP1), were significantly associated with migraine compared to non-migraine headache, underlining the specificity of these variants for migraine." (PMID 22072275, 2012). "While rs2651899 (PRDM16), rs10166942 (TRPM8), and rs11172113 (LRP1) appear most important for common migraine (i.e., at the population level), rs1835740 may play the major role in more severe forms of migraine (i.e., clinic-based populations)." (PMID 22072275, 2012).